PAX6 (paired box 6)
Diseases named in the same sentence as PAX6 in open-access papers (continued):
Sharing a sentence is not in itself a finding about the gene and the disease.
WAGR syndrome (37 papers, 2005 to 2025). WAGR syndrome (Wilms tumor - aniridia - genitourinary anomalies - intellectual disability mental retardation) is a rare genetic disorder characterized by an unusual complex of congenital developmental abnormalities with intellectual disability, and an increased risk of developing Wilms tumor. "Altered expression of the transcription factor Pax6 in the dorsal striatum (DStr) has been linked to cognitive and behavioral impairments observed in neurodevelopmental disorders, including WAGR syndrome and autism." (PMID 41002437, 2025). "Heterozygous pathogenic variants in PAX6 are typically associated with autosomal dominant aniridia, or are part of the Wilms tumor-aniridia-genital anomalies-range of developmental delay (WAGR) syndrome if the whole gene is deleted along with WT1." (PMID 41011222, 2025). "The size of deletion of 11p13 varies between 1 megabase to 26.5 megabase; however, even a 700 kilobase deletion deleting both WT1 and PAX6 genes can cause WAGR syndrome." (PMID 39600756, 2024). "Expanding our knowledge on the SCO focusing on Pax6 would be beneficial to understand congenital hydrocephalus because clinical cases of hydrocephalus have been reported in WAGR syndrome, in which PAX6 is one of the causative genes." (PMID 35638289, 2022). "The deletion of chromosome 11p13 involving the WT1 and the PAX6 genes has been shown to cause WAGR syndrome." (PMID 36011342, 2022). "Neural behavior analysis for Pax6-null mice/rats and investigation of clinical patients with Gillespie or WAGR syndrome indicated that Pax6 is associated with cerebellar ataxia and other neurologic diseases." (PMID 34111112, 2021). "WAGR syndrome is caused by hemizygous deletions of 11p13 that remove one copy of PAX6 and one copy of WT1." (PMID 15918896, 2005). "Deleted genes in the region including WT1 and PAX6 are thought to cause the phenotypic features and clinical issues in patients; however, much is still unknown about the specific molecular role of these genes in patients with WAGR syndrome." (PMID 34970513, 2021). "In one child with WAGR syndrome, caused by deletion of not only WT1 but also neighbouring genes including PAX6, the Wilms tumour harboured gain of chromosome 1." (PMID 39665570, 2025). "Approximately one third of patients with sporadic aniridia ultimately develop WAGR syndrome due to a contiguous gene deletion syndrome involving both PAX6 and WT1." (PMID 34573386, 2021). "Just as PAX6 has served as a model for dosage-sensitive transcription factors, WAGR syndrome is a paradigm for contiguous deletion syndromes." (PMID 30242502, 2019). "The best known syndromic form is WAGR syndrome (OMIM 194072) — a contiguous genes deletion syndrome of the 11p13 region (encompassing the PAX6 and WT1 genes)." (PMID 29460221, 2018). "Human PAX6 gene was originally identified in the chromosome region 11p13 that is responsible for WAGR syndrome." (PMID 27855195, 2016). "The typical deletion in WAGR syndrome includes the WT1 and PAX6 genes, but larger deletions can be associated with obesity and neurobehavioral abnormalities." (PMID 26605098, 2015). "Eight probes were screened in the 11p13 region associated with WAGR syndrome, in BDNF (2 probes), PAX6 (3 probes), WT1 (2 probes) and HIPK3 (1 probe)." (PMID 18925931, 2008). "Therefore, the concurrent deletion of the SIMO element and PAX6 gene in WAGR syndrome leads to a more severe ocular phenotype." (PMID 36011342, 2022). "According to our observations, simultaneous loss of the PAX6 and ARL14EP genes by a single deletion in patients with WAGR syndrome may effectively act as a double hit that worsens the lens damage caused by the deletion of PAX6." (PMID 36011342, 2022). "The deletion located in the region 11p14.1p13 included, among others, the WT1 (MIM #607102) and PAX6 (MIM #607108) genes, which correlated with the clinical phenotype of WAGR syndrome in the patient." (PMID 38069245, 2023).
WAGR syndrome (continued). "A small proportion of the sporadic cases have WAGR syndrome (OMIM194072), a 11p13 contiguous gene deletion syndrome involving PAX6 and WT1 genes." (PMID 35614435, 2022). "We identified different heterozygous deletions affecting the PAX6 and WT1 genes on chromosome 11p13 in all six probands with WAGR syndrome." (PMID 36011342, 2022). "Therefore, this study suggested that haploinsufficiencies of PAX6 or PRRG4 included in this region were candidate genes for severe developmental delay and autistic features characteristic of WAGR syndrome." (PMID 26605098, 2015). "In two children diagnosed with WAGR syndrome, one child (No. 31) was diagnosed with nephroblastoma via renal ultrasound examination based on the implications of a positive genetic test with a large deletion covering PAX6 and WT1." (PMID 39449022, 2024). "The infant's genetic testing confirmed a heterozygous alteration in Exon 7 of PAX6 (c.495delG, p.Thr166Leufs*41) and a negative WT1 which excluded WAGR syndrome." (PMID 32056389, 2020). "Genetic testing confirmed a heterozygous alteration in PAX6 (c.495delG, p.Thr166Leufs*41) and no abnormalities of WT1, excluding WAGR syndrome." (PMID 32056389, 2020).
diabetes (36 papers, 2011 to 2026). "As beta cell loss is a hallmark of both T1D and T2D, we examined the potential participation of PAX6 in diabetes‐associated beta cell loss by treating EndoC‐βH1 cells with high glucose and palmitic acid (HGPA) to mimic the diabetic condition." (PMID 37933577, 2023). "The expression pattern of PAX6 is consistent with the diverse eye defects, brain abnormalities and diabetes observed in humans with PAX6 mutations." (PMID 36202929, 2023). "Augmentation of PAX6 expression or activity thus represents a promising approach to reverse beta cell loss in diabetes." (PMID 37933577, 2023). "Several studies have shown that PAX6 protein-truncating mutations in aniridia pedigrees also co-segregate with diabetes and glucose intolerance." (PMID 36202929, 2023). "A limited number of cases of diabetes mellitus in adults with a PAX6 mutation suggest that the gene also plays a role in glucose homeostasis." (PMID 34200146, 2021). "It is also expressed in the early pancreatic bud and is necessary for insulin homeostasis in the adult pancreas; Pax6 deletion rapidly leads to classical diabetes and weight loss." (PMID 30007277, 2018). "These tune tissue-specific PAX6 gene expression, can be modulated by common genetic variants and further implicate the Pax6 locus in pancreas function and diabetes." (PMID 30007277, 2018). "Genome-wide association studies have revealed that variants located in regulatory elements for pancreatic transcription factors are linked to diabetes, including those functionally linked to the paired box transcription factor Pax6." (PMID 30007277, 2018). "Homozygous PAX6 deleted mice showed symptoms of diabetes and severe weight loss, which points to a possible connection between PAX6-associated SNPs and metabolic function." (PMID 24695378, 2014). "There have also been reports of glucose intolerance and predisposition to diabetes in some individuals, and in some rodent models, with heterozygous PAX6 mutations." (PMID 23326594, 2013). "Down-regulation of PAX6 expression is implicated in beta cell dysfunction in diabetes." (PMID 38844555, 2024). "Pax6 deletions in adult mice cause rapid onset of classic diabetes, but the full spectrum of pancreatic Pax6 regulators is unknown." (PMID 30007277, 2018). "It was found that the expression of NeuroD1-βcellulin reversed diabetes and maintained normoglycaemia, with associated up-regulation of both upstream and downstream β-cell transcription factors, including Pdx1, Pax6, Pax4, Nkx2.2, and Nkx6.1, as seen in the current study." (PMID 27070593, 2016). "In addition, mice with heterozygous Pax6 mutations develop diabetes, suggesting Pax6 also regulates glucose metabolism." (PMID 23056534, 2012). "This study also provides a complete molecular mechanism for the Pax6 deficiency-caused diabetes." (PMID 23056534, 2012). "Because these factors—including GLIS3, PAX6, GATA6, HNF1B, and NEUROG3—are pleiotropic regulators active in multiple organ systems, their deficiency rarely causes isolated diabetes." (PMID 41614934, 2026). "Pax6 has been considered as a candidate gene for diabetes due to its role in transcriptional regulation of β-cell insulin secretion." (PMID 38356808, 2024). "In this commentary, we summarize the roles of PDX1, MAFA, and PAX6 in determining beta cell function and diabetes development." (PMID 38844555, 2024). "The well-established functional role of PAX6 in glucose-induced insulin secretion and the co-segregation of diabetes in families with aniridia provide compelling support for the pathogenicity of this mutation for diabetes." (PMID 36202929, 2023). "Nevertheless, these findings suggest that PAX6 functions as either a direct or indirect activator or repressor of genes in human beta cells that determines beta cell function and diabetes development." (PMID 37933577, 2023).
diabetes (continued). "We then adopted an adeno‐associated virus (AAV) approach to overexpress PAX6 in beta cells in order to investigate the therapeutic potential of PAX6 in beta cell survival and diabetes management." (PMID 37933577, 2023). "STZ administration led to the development of overt diabetes and a significant diminution of PAX6 protein expression in pancreas." (PMID 37933577, 2023). "In the present study, we made several notable observations concerning the role of PAX6 in beta cell preservation and diabetes management." (PMID 37933577, 2023). "Given the prevalence of diabetes worldwide, our findings provide grounds to support the future clinical translation of PAX6 gene delivery to overcome beta cell failure in diabetes." (PMID 37933577, 2023). "PAX6 is an important gene involved in a series of diseases including eye diseases, diabetes, autism spectrum disorder and mesiodens." (PMID 31133012, 2019). "The molecular mechanisms responsible for downregulation of Pax6 transcription in diabetes remain to be elucidated." (PMID 28270834, 2017). "Elimination of PAX6 activity, an epigenetic result of uterine artery occlusion induces diabetes and a dramatic reduction in the number of beta cells producing insulin in the intrauterine growth restricted rodent model." (PMID 29326659, 2017). "Mice with conditional inactivation of Pax6 in Pdx1 or Pax6 expression domains died few days postpartum and suffered from diabetes." (PMID 26658466, 2015). "Therefore, our results in targeting miRNA regulation of PAX6 pancreatic expression have potentially broad implications for therapy of prediabetes and diabetes." (PMID 30290306, 2018). "Both PAX4 and PAX6 have a well-established link to diabetes phenotypes." (PMID 30007277, 2018). "This suggests PAX6 has a broader role in the pathophysiology of diabetes in some populations." (PMID 30290306, 2018). "Small eye mice are homozygous for a mutation in the Pax6 gene and are reported to have no lenses, an identical phenotype to that observed in Daam1gt/+ embryos that had been exposed to maternal diabetes." (PMID 25540130, 2015). "Homozygous Pax6 deletion mice, but not controls, presented with all the symptoms of classical diabetes leading to severe weight loss requiring termination of the experiment five weeks after first tamoxifen administration." (PMID 23326594, 2013). "The inherited expression of Isl-1/Pax-6/Nkx6.1/Somatostatin transcripts in h-ASCs, its ease in availability and autologous origin, make it an eminent candidate for cell replacement therapy in diabetes." (PMID 21687731, 2011). "We hypothesized that additional missense mutations in PAX6 that cause monogenic-like diabetes in the absence of eye abnormalities exist in humans." (PMID 36202929, 2023). "Therefore, the detection of a likely pathogenic missense mutation in PAX6 in a family with dominant diabetes without overt ocular phenotypes is not so surprising." (PMID 36202929, 2023). "EZH2 represses the transcription factor Pax6, which controls expression of the antioxidant inhibitor TXNIP, and in diabetes, downregulation of EZH2 promotes oxidative stress." (PMID 37144033, 2023). "Our results expand the spectrum of PAX6 genotype-phenotype relationships from aniridia with diabetes to adult-onset diabetes without eye defects." (PMID 36202929, 2023). "We also note that in this case, relevance to the situation in human diabetes is not yet proven; we have observed downregualtion of Pax6 in diabetic db/db mice but not in islets from humans with T2D." (PMID 28270834, 2017). "Homozygous Pax6 deletion mice, but not controls, presented with symptoms of diabetes." (PMID 27231702, 2016).
myopia (34 papers, 2007 to 2026). "The C allele rs662702 of the PAX6 gene increases the risk of myopia, and the expression of miR-328 in the blood cells of myopic patients is higher than that of the average group 46." (PMID 40657400, 2025). "The PAX6 gene, which plays a vital role in the development of the eyes, has been associated with both high and extreme myopia, highlighting its significance in the development of refractive errors." (PMID 39767875, 2024). "Increases in the length of the PAX6 P1 promoter AG dinucleotide repeatedly affect the transcription activity and are associated with high myopia." (PMID 35327754, 2022). "PAX6 was also identified to be hypermethylated by 3-fold at the 5’UTR in association with myopia in our study." (PMID 30858441, 2019). "Mutations in the binding site of miR-328 within 3’-UTR of a myopia-causing gene Pax6 were also shown to be associated with high myopia in a Chinese cohort, suggesting that miRNAs play an important role in refractive eye development as well." (PMID 27622715, 2016). "It was reported that a SNP located within the miR-328 binding site in the 3’-UTR of PAX6 reduced PAX6 protein levels and was significantly associated with extreme myopia in a Chinese cohort." (PMID 27622715, 2016). "The current study is the first study to prove significant associations between a PAX6 SNP and high myopia and extreme myopia." (PMID 23213273, 2012). "Two Chinese reports also denied an association of PAX6 with high myopia, while the subgroup analysis showed PAX6 was associated with extreme myopia." (PMID 23213273, 2012). "PAX6 has a central role in eye development and has also been shown to be associated with high myopia." (PMID 22792142, 2012). "In conclusion, we proved the significant association of rs644242 in PAX6 with high and extreme myopia." (PMID 23213273, 2012). "Microphthalmia transcription factor (Mitf) is associated with ocular albinism, and paired box 6 (PAX6) has been associated with retinal degeneration, extreme myopia, and corneal innervation." (PMID 22539872, 2012). "The current study showed a significant association of PAX6 with high and extreme myopia in Japanese participants." (PMID 23213273, 2012). "In the present study, using a relatively large cohort of 2,563 individuals, we showed that PAX6 is associated with high and extreme myopia in Japanese." (PMID 23213273, 2012). "PAX6 was first reported as a candidate gene for myopia in a genome-wide linkage scan for myopia susceptibility loci in a twin study, and was in fact directly below the highest peak at the 11p13 locus – the MYP7 locus." (PMID 21589860, 2011). "In conclusion, several haplotypes in the 3′ end of the PAX6 locus were found to be associated with high myopia in both the initial study and the replication study involving Han Chinese subjects." (PMID 21589860, 2011). "The initial study provided convincing evidence for the association of 3′ PAX6 haplotypes with high myopia in Chinese." (PMID 21589860, 2011). "With both initial and replication testing, we confirm that 3′ PAX6 haplotypes are associated with high myopia in our Chinese population." (PMID 21589860, 2011). "This study investigated the association of PAX6 with high myopia in 379 high myopia patients and 349 controls." (PMID 19907666, 2009). "Intronic sequence alterations (SNPs) in PAX6 have been reported to associate with high myopia in Han Chinese nuclear families and with extreme myopia in a Taiwan Chinese population, but not in Caucasians." (PMID 19907666, 2009). "Results of our genotyping and promoter activity analyses indicate that longer lengths of dinucleotide repeats increase the expression of PAX6, which increases the risk of high myopia." (PMID 19907666, 2009). "Our results revealed an association between high myopia and AC and AG dinucleotide repeat lengths in the PAX6 P1 promoter, indicating the involvement of PAX6 in the pathogenesis of high myopia." (PMID 19907666, 2009).